NSMCE4A (NSE4A component of SMC5/6 complex)
Description:
Component of the SMC5-SMC6 complex, a complex involved in DNA double-strand breaks by homologous recombination. The complex may promote sister chromatid homologous recombination by recruiting the SMC1-SMC3 cohesin complex to double-strand breaks. The complex is required for telomere maintenance via recombination in ALT (alternative lengthening of telomeres) cell lines and mediates sumoylation of shelterin complex (telosome) components which is proposed to lead to shelterin complex disassembly in ALT-associated PML bodies (APBs). Is involved in positive regulation of response to DNA damage stimulus.
Synonyms: NS4EA; C10orf86; FLJ20003; bA500G22.3; NSE4A
Tractability: PROTAC: ubiquitination databases record sites on it; its protein half-life has been measured.
Gene: Protein-coding gene on chromosome 10 (121,953,334 to 121,975,257, reverse strand). Ensembl gene ENSG00000107672.
Subcellular location: Nucleus; Chromosome, telomere
Subcellular location (Human Protein Atlas): Nucleoplasm
Pathways (Reactome):
Metabolism of proteins: SUMOylation of DNA damage response and repair proteins
Gene Ontology:
Molecular function: protein binding
Biological process: DNA damage response; chromatin looping; DNA repair; double-strand break repair via homologous recombination; protein sumoylation; regulation of telomere maintenance
Cellular component: nucleoplasm; Smc5-Smc6 complex; chromosome, telomeric region; nucleus; chromosome
Genetic constraint (gnomAD): Loss-of-function variants: 22 observed, 25.04 expected, observed/expected ratio (o/e) 0.88, 90% interval 0.63 to 1.25. The upper end of that interval is the gene's LOEUF score, 1.25, which puts it in group 5 of 6, group 1 being the genes least tolerant of losing a copy. Missense variants: 377 observed, 326.09 expected, observed/expected ratio (o/e) 1.16, 90% interval 1.06 to 1.26. Synonymous variants: 124 observed, 115.06 expected, observed/expected ratio (o/e) 1.08, 90% interval 0.93 to 1.25.
Homologues: Orthologues: chimpanzee NSMCE4A (99% identical), macaque NSMCE4A (98% identical), dog NSMCE4A (89% identical), rat Nsmce4a (88% identical), mouse Nsmce4a (87% identical), pig NSMCE4A (86% identical), rabbit NSMCE4A (85% identical), guinea pig NSMCE4A (84% identical), tropical clawed frog nsmce4a (47% identical). Paralogues in human: EID3 (43% identical).
Diseases named in the same sentence as NSMCE4A in open-access papers:
NSMCE4A is named in the same sentence as 2 diseases in open-access papers, as found by Europe PMC text mining. Sharing a sentence is not in itself a finding about the gene and the disease.
NSMCE4A shares sentences with these, for which no sentence is quoted: cancer (1 paper); infection (1).